ICAM1 (intercellular adhesion molecule 1)
Diseases named in the same sentence as ICAM1 in open-access papers (continued):
Sharing a sentence is not in itself a finding about the gene and the disease.
ischemic stroke (continued). "TMEM16A is upregulated after ischemic stroke, and knockdown of TMEM16A in brain endothelial cells leads to attenuation of inflammation through the decrease in activation of nuclear factor kappa-light-chain-enhancer of activated B cells (NF-κB) and intercellular adhesion molecule 1 (ICAM-1)." (PMID 38791133, 2024). "However, the association of ICAM1 and PTGS2 expression with sex differences in ischaemic stroke has not been previously reported." (PMID 34792838, 2022). "However, targeting ICAM-1 in ischemic stroke patients is not a viable therapeutic strategy as using anti-ICAM-1 antibody led to worse clinical outcomes in a clinical trial of 625 ischemic stroke patients." (PMID 36277770, 2022). "Hence, without imaging leukocyte adhesion in vivo after ischemic stroke in these animals, a final statement on the role of ICAM-1 for ischemic tissue injury may be premature." (PMID 35140676, 2021). "Blood levels of ICAM-1, VCAM-1, and E-selectin were higher in ischemic stroke patients than in TIA patients, without a correlation of infarct volume with functional outcome." (PMID 32595585, 2020). "This is in line with our findings demonstrating significantly increased plasma ICAM-1 and VCAM-1 levels in ischemic stroke patients compared to controls although we observed no change in E-selectin." (PMID 32595585, 2020).
ischemia (75 papers, 2007 to 2025). A hypoperfusion of the BLOOD through an organ or tissue caused by a PATHOLOGIC CONSTRICTION or obstruction of its BLOOD VESSELS, or an absence of BLOOD CIRCULATION. "In ICAM‐1‐deficient mice, transient focal ischemia resulted in significantly reduced infarct volumes when compared with wild‐type mice, indicating that ICAM‐1‐mediated neutrophil adhesion contributes to ischemic damage." (PMID 41498036, 2025). "Under normal circumstance, the levels of ICAM-1 are low and are upregulated by cytokines after ischemia, which in turn causes inflammatory response and aggravates ischemic brain injury." (PMID 33927611, 2021). "Furthermore, elevated ICAM-1 expression has been linked to ischemia in older adults." (PMID 39195236, 2024). "In contrast, the rescue group exhibited more pronounced pathological damage in the brain tissue, with exacerbated disruption of the neurovascular unit, suggesting that overexpression of ICAM1 worsened brain tissue injury and ischemia." (PMID 41404041, 2025). "In the immediate aftermath of ischemia, endothelial cells begin to upregulate the expression of adhesion molecules, such as intercellular adhesion molecule 1 (ICAM-1), vascular cell adhesion molecule 1 (VCAM-1), P-selectin, and E-selectin." (PMID 39582857, 2024). "Intravenous infusion of ASOs against ICAM-1 reduced ICAM-1 expression in kidney endothelium and protected renal function subjected to ischemia injury alone or in combination with transplantation." (PMID 36735106, 2023). "Cold ischemia leads to expression of P-selectin and ICAM-1 on the endothelium, and augments allogeneic-mediated cell infiltration in rat kidney allografts." (PMID 35185378, 2022). "The combination of LFA-1 and ICAM1 facilitate leukocyte adherence to, or passage through vascular endothelial cells to reach the focal area of ischemia." (PMID 34017247, 2021). "AIM2 deletion in brain endothelial cells reversed ischemia‐induced BBB injury by suppressing ICAM‐1 expression and neutrophil adhesion in a STAT3 signaling‐ dependent manner." (PMID 34156153, 2021). "The activated NF-κB and increased CAMs such as ICAM-1 are essential factors involved in ischemia-induced BBB damage." (PMID 32264912, 2020). "NBP treatment significantly inhibited the upregulation of PAR-1 and ICAM-1 in brain endothelial cells after ischemia." (PMID 31595195, 2019). "The selective inhibitor of NF-κB also alleviated the disruption of BBB permeability, confirming that NF-κB and ICAM-1 upregulation are essential factors involved in ischemia-induced BBB damage." (PMID 31447648, 2019). "We observed here that ICAM-1 levels significantly increased in heart tissues after 2 h of myocardial ischemia reperfusion, suggesting ischemia induces inflammatory responses in the heart." (PMID 29467653, 2018). "ROS induce intercellular adhesion molecule-1 (ICAM-1) and vascular cell adhesion molecule-1 (VCAM-1) which recruit leukocytes to the region with ischemia/reperfusion injury and cause a secondary disorder." (PMID 30513734, 2018). "Second, red wine suppressed ischemia-induced expression of ICAM-1, P-selectin and L-selectin and ethanol delineated ischemia-induced expression of ICAM-1, E-selectin and L-selectin." (PMID 28970514, 2017). "Next, intercellular adhesion molecule-1 (ICAM-1) upregulation in ischemia has been noted to increase EPC recruitment to ischemic limbs." (PMID 28232850, 2017). "The etiologic role of released IL-6 in stimulation of myocyte ICAM-1 was previously demonstrated by others, and binding of neutrophils to ICAM-1 is considered to be a causal factor in myocyte injury after ischemia." (PMID 26935770, 2016). "Increased parasite adhesion to ICAM-1 in children with evidence of intestinal ischaemia lends further evidence to a link between the cytoadherence of iRBCs in gut microvasculature and intestinal damage." (PMID 26830671, 2016).
ischemia (continued). "In the ischemia group the ICAM-1 mRNA expression in the myocardial tissues of the rats was significantly increased compared with that in the sham surgery group (P<0.01)." (PMID 25667680, 2015). "Once ischemia occurs, multiple inflammatory factors induce the overexpression of ICAM-1 in microvascular endothelial cells." (PMID 26035181, 2015). "Consistently, serum levels of ICAM-1 in rabbits were induced after the initiation of ischemia and uproar after reperfusion in our study." (PMID 23056624, 2012). "Pretreatment with topical polyethylene glycol hydrogel delivery of ICAM-1 antisense oligonucleotides demonstrated decreased ICAM-1 mRNA expression, reduced ICAM-1 protein staining, and decreased cellular damage in a murine partial nephrectomy/ischemia model." (PMID 20182538, 2009). "Our result showed that ICAM-1 expression was significantly augmented after treatment with the unconditioned protein supplemented at the beginning of ischemia and even more when exposed to hypoxia-preconditioned α-Syn in comparison to nontreated ischemic or control cells." (PMID 40964705, 2025). "Detection of ischemia through intercellular adhesion molecule-1 (ICAM-1) mediated targeting of endothelial cells, P-selectin targeted detection are some of the advancements in the field of cardiac ultrasound technology over the conventional reperfusion-based methods." (PMID 36756211, 2023). "Adhesion molecules (Icam-1 and Vcam-1) reflect the reperfusion phase of inflammatoryreaction to ischemia in which leukocytes adhere to the endothelium, increasingvessel permeability, amplifying the inflammatory reaction by the migration of moreinflammatory cells." (PMID 34755767, 2021). "Therefore, during ischemia, the blood flow through the capillaries is reduced, and with the effect of adhesion factors, such as ICAM-1 and CD62L, these leukocytes are more likely to sink into the capillaries, and eventually lead to NR." (PMID 33628178, 2020). "In summary, our research demonstrated that inhibiting the aberrant upregulation of TMEM16A could reverse ischemia-induced BBB injury by downregulating ICAM-1 levels in an NF-κB signaling dependent manner." (PMID 31447648, 2019). "Finally, NF-κB inhibitor treatment also alleviated OGD/ R-induced BBB permeability, confirming that activated NF-κB and increased ICAM-1 are essential factors involved in ischemia-induced BBB damage." (PMID 31447648, 2019). "ICAM-1 has been shown to be upregulated in myocardium after ischemia." (PMID 31312919, 2019). "The overexpression of EN might affect two factors which are involved in acute inflammatory response, reperfusion and ischemia injury and antitumor response: LFA-1 (lymphocyte function-associated antigen-1) and ICAM-1 (intercellular adhesion molecule-1)." (PMID 28056805, 2017). "Cell-adhesion molecules, particularly ICAM-1, are induced during the early stages of ischemia by TNF-α, along with other proinflammatory cytokines; subsequently, leukocytes begin to firmly adhere to endothelial cells, from where they can infiltrate into the brain tissue." (PMID 23972823, 2013). "Whether pro-inflammatory ICAM-1+ neutrophils, which are believed to be induced by eCIRP, are the predominant subpopulation in CIRP-wildtype mice experiencing ischemia and ICAM-1+ originated NETs also have the same effect on angiogenesis needs to be further investigated." (PMID 33916904, 2021). "Therefore, we measured the expression of ICAM‐1 in the context of AIM2 deletion and found that both MCAO and OGD/R increased ICAM‐1 expression, whereas inhibiting AIM2 reversed these effects, suggesting that AIM2 deletion prevents ischemia‐induced BBB injury by downregulating ICAM‐1 expression." (PMID 34156153, 2021). "The increased expression of TNF-α after ischemia may up-regulate adhesion molecules such as ICAM-1, which can damage the endothelium and BBB, Overexpression of TNF-α exacerbates ischemic cerebral damage, whereas their inhibition decreases cerebral edema and infarct volume." (PMID 28486941, 2017).
ischemia (continued). "ICAM-1 neuronal immunoreactivity was occasionally observed in the sham-operated animals, increased in number and fluorescent intensity after 3 days of reperfusion following 8 min of ischemia, and were further aggravated by hyperglycemic ischemia and reperfusion." (PMID 25389378, 2014). "In the present study, we observed that ICAM-1 mRNA and protein levels dramatically increased in brain cortical tissues after 1, 3 and 6 days of recovery following 8 min of forebrain cerebral ischemia, suggesting ischemia induces inflammatory responses in the brain." (PMID 25389378, 2014). "Also, in an ischemia model, both intraischemic and delayed hypothermia decreased intercellular adhesion molecule-1 (ICAM-1) expression, which might play a significant role in cell extravasation and migration." (PMID 22776061, 2012). "In vitro, brain microvascular endothelial cells upregulated ICAM-1, IL-6, and VEGFR-2 expression when exposed to recombinant α-Syn at the beginning of ischemia and to a larger extent when α-Syn was preconditioned for 18 hours in hypoxia." (PMID 40964705, 2025). "Inflammatory signaling is activated and completed by blood-derived leukocytes, which penetrate the brain during ischemia and produce inflammatory cytokines and proinflammatory mediators, including TNF-α, IL-6, and ICAM-1." (PMID 37361203, 2023). "Although it has been reported that compared with ICAM-1, the increased expression of VCAM-1 is more closely related to the degree of ischemia and hypoxia of the retina and the formation of NPAs and NV." (PMID 35967519, 2022). "Treatment with PEDF34-NP significantly reduced the ischemia-induced retinal VEGF (27%, p < 0.05) and ICAM-1 (31%, p < 0.01) in OIR rat retinas, compared with those of retina with Control-NP injection." (PMID 36589744, 2022). "Pioglitazone was found to inhibit TNFα-induced expression of ICAM-1 and VCAM-1 in activated cultured endothelial cells and an ischemia/reperfusion renal injury model." (PMID 34831270, 2021). "Next, we investigated the expression of ICAM-1 and VCAM-1 in the dorsal skinfold chamber tissue after 3 h ischemia and 3 h reperfusion by means of Western blot." (PMID 30992483, 2019). "Consistently, we found that ischemia-induced TREM-1 promoted IL-1β, IL-18, IL-6, CXCL-2, MCP-1, and CXCL-1 productions in microglia as well as the expression of MPO and ICAM-1 following ischemic injury." (PMID 31324751, 2019). "MSCs exerted a potent regulating function on endothelial ICAM-1 expression, which consequently attenuated neutrophil infiltration, MMP-9 function, and ischemia-induced BBB disruption." (PMID 29724240, 2018). "In immunofluorescence staining, expression levels of ICAM-1 and VCAM-1 were significantly decreased in the microvessels of the Sac-1004-ischemia group 3 h after I/R compared with those in the vehicle-ischemia group." (PMID 28645333, 2017). "The incremental inductions of ICAM-1 and VCAM after indomethacin treatment were responsible for ischemia and aggravated organ damages, in which either vascular inflammation or increased leukocyte aggregation was engaged." (PMID 23066659, 2012). "TNFα and IL-1 have been shown to cause up-regulation of E-selectin, ICAM-1, ICAM-2, and VCAM-1 on cerebral endothelial cells and the induction of such adhesion molecules may explain the elevation of TNFα and IL-1 levels after ischemia increases neutrophil infiltration." (PMID 22196138, 2011). "Recent studies indicate that in hepatic ischemia reperfusion injury, blocking ICAM-1 reduced inflammation and liver injury, and ICAM-1 immunoblockade has been considered as a possible target for therapeutic intervention." (PMID 17868448, 2007). "Brain neutrophil infiltration and ischemia damage are both reduced in animals lacking ICAM-1 or treated with techniques that block ICAM-1." (PMID 36904106, 2023).
ischemia (continued). "CCL-2 infusion of the femoral artery of rabbits following hindlimb ischemia increased monocyte accumulation in the vessel wall; a finding that was inhibited with ICAM-1 monoclonal antibody treatment, suggesting that monocyte adhesion to the endothelium in ischemia involves CCL-2 and ICAM-1." (PMID 36465438, 2022). "Furthermore, the expressions of HIF-1a, VEGF, PDGF, VCAM-1, and ICAM-1 mRNA were all significantly increased in WIRS control group, signifying that pathogenesis of WIRS was related to ischemia and defective blood supply." (PMID 32801474, 2020). "ICAM‐1 and VCAM‐1 are the adhesive molecules that also play a regulatory role during inflammation, mediated leukocyte migration into the injured CNS, and contribute to ischemia‐induced neuroinflammation." (PMID 29201553, 2017). "Blocking ICAM-1 interrupts the process of neutrophil adhesion to the endothelium and, in turn, prevented neutrophil transmigration out of the blood vessel in a rodent model of ischemia/reperfusion, but not in permanent ischemia." (PMID 37959180, 2023). "In the ischemia + PPG group, the TNF-α, IL-1β and IL-6 levels in the serum were significantly increased, the expression of ICAM-1 mRNA was increased, although without a significant difference, and the expression of NF-κB was increased." (PMID 25667680, 2015). "Similarly, ICAM-1 and VCAM-1 mRNA levels were increased in the brain tissue of Poldip2+/+ mice after ischemia, but not in Poldip2+/− mice." (PMID 33692398, 2021). "Compared with the ischemia group, the ICAM-1 mRNA expression in the myocardial tissues of the rats was reduced in the ischemia + low-, medium- and high-dose NaHS groups (P<0.05 or P<0.01); ICAM-1 mRNA expression was increased markedly, but not significantly, in the ischemia + PPG group (P>0.05)." (PMID 25667680, 2015).
colitis (73 papers, 2009 to 2025). Inflammation of the colon. "Along the same lines, in an experimental mouse model of colitis induced by dextran sodium sulphate, ICAM-1 deficiency protected mice against severe forms of the disease, with lower mortality and the absence of clinical symptoms." (PMID 38391953, 2024). "Specifically, ICAM-1-deficient Treg cells show impaired activation and control of colon inflammation in an experimental mouse model of colitis." (PMID 38391953, 2024). "Anti-ICAM-1 antibodies have been shown to reduce colitis and prolong the survival of dss-induced ICAM-1-deficient mice." (PMID 36118873, 2022). "Finally, using the Winnie mouse model of colitis, we showed that the blockage of ICAM-1/lymphocyte function-associated antigen-1 (LFA-1) with lifitegrast reduced colitis severity and decreased T-cell infiltration in the myenteric plexus." (PMID 38428588, 2024). "In the experimental colitis model, a prominent feature of rM-ed neutrophils was the high expression of ICAM-1, with the mean fluorescence intensity (MFI) level significantly higher than that of resident neutrophils in the blood." (PMID 41417165, 2025). "Endothelial cells enhanced the expression of ICAM-1 and VCAM-1 in the experimental colitis model caused by trinitrobenzene sulfonic acid, increasing leukocyte recruitment to the inflammatory bowel, which was consistent with our result." (PMID 40224490, 2025). "ICAM1 expression in the cortex was significantly increased in response to acute colitis, while a trend toward increased expression was observed in the hippocampus." (PMID 40457749, 2025). "Intercellular adhesion molecule 1 (ICAM1), abundantly expressed in colonic mucosal macrophages from colitis mice and IBD patients, plays a crucial role in promoting efferocytosis and maintaining homeostasis." (PMID 40657202, 2025). "ICAM1 is thought to have a central role in IBD conditions and treatment with anti-ICAM1 antibodies reduces colitis symptoms in rodents." (PMID 39080343, 2024). "Studies in a mouse model of dextran sulphate sodium-induced colitis demonstrated increased ICAM-1 expression with disease activity." (PMID 38543230, 2024). "Intraperitoneal administration of anti-ICAM-1 antibody has been shown to greatly reduce tissue damage in a model of colitis induced by dextran sodium sulphate in rats." (PMID 37237555, 2023). "In the tumors of colitis mice, surface expression of ICAM-1 on CD31+ vascular endothelial cells reduced significantly as comparison to that of normal mice." (PMID 37605139, 2023). "Targeting ICAM1 was shown to effectively alleviate inflammation, reduce bloody stools and anemia in murine model of colitis." (PMID 36860851, 2023). "The microvascular expression of ICAM-1 is increased in IBD patients, and ICAM-1 has been shown to be crucial to T-cell recruitment in the T-cell transfer murine colitis model." (PMID 36982601, 2023). "Colonic endothelial cells are by and large ICAM1-negative under the homeostatic state, while are remarkably up-regulated with ICAM1 expression during colitis, consistent with what we discovered here." (PMID 36860851, 2023). "Multiplex staining validated the reduced ICAM-1 expression on tumor vascular endothelium of colitis mice." (PMID 37605139, 2023). "Similar results were reported in another study showing that ICAM-1 blockade diminished leukocyte adhesion in colonic venules in a rat model of colitis induced by trinitrobenzene sulfonic acid." (PMID 37237555, 2023). "The results showed that FBPE at 25.2 g/kg body weight (g/kg BW) changed the clinical symptoms of colitis, the ICAM-1 expression in colon, the activity of related inflammatory mediators in colon tissue and helped restore the immune system." (PMID 35564016, 2022). "In this study, we also evaluated the intestinal expression of ICAM-1 and P-selectin that contribute to cell recruitment during colon inflammation." (PMID 33445622, 2021).